GDF10 (growth differentiation factor 10)
Diseases named in the same sentence as GDF10 in open-access papers (continued):
Sharing a sentence is not in itself a finding about the gene and the disease.
tumor (continued). "Briefly, the studies showed that growth differentiation factor 10 (GDF10) promotes the functional transformation of an NF to a CAF via LOC100506114 that binds to the transcription factor RUNX2, which, in turn, participates in tumor growth, invasion, and metastasis." (PMID 36899863, 2023). "In addition, we saw no obvious difference in PGM5-AS1, miR-587 or GDF10 expression in tumor tissues from untreated mice compared with those treated with oe-NC (p > 0.05), and likewise no appreciable difference in tumor size and weight (p > 0.05)." (PMID 33407592, 2021).
cancer (17 papers, 2005 to 2026). A tumor composed of atypical neoplastic, often pleomorphic cells that invade other tissues. "The reduced GDF10 expressioncharacteristic of this type of cancer is associated with a decrease in theoverall survival rate." (PMID 33173593, 2020). "Our data point to the need for more research to understand how to target GDF10 in anti-cancer therapy." (PMID 42111348, 2026). "GDF10 (BMP3b) is a TGF-ß superfamily ligand with little knowledge of its role in cancer progression." (PMID 42111348, 2026). "GDF10 is vital in cell proliferation and differentiation, and it inhibits several types of cancer by acting as a tumor suppressor too." (PMID 36262352, 2022). "Growth differentiation factor-10 (GDF10) with its methylation trait has recently been found to play a crucial regulatory and communication role in cancers." (PMID 36262352, 2022). "Here is the first time that the specific methylation sites of GDF10 been able to draw on some systematic research into cancer." (PMID 36262352, 2022). "They validated that the anti-cancer role of PGM5-AS1 in PC cells was achieved by binding to miR-587 to promote the expression of GDF10." (PMID 35525925, 2022). "We further validated that the anti-cancer role of PGM5-AS1 in PCa cells was achieved by binding to miR-587 to promote the expression of GDF10." (PMID 33407592, 2021). "Similarly, of the genes associated with CIN3/cancer, C1RL, GDF10, and GDF2 were also associated with persistence (p-values of 0.00875, 0.0423, and 0.04080, respectively)." (PMID 22496757, 2012). "This suggests a direct link between GDF10-mediated TGF-β signaling, EMT, and the metastatic capacity of TNBC cells and supports the idea that GDF10 inhibits cancer growth at least in part by inhibiting EMT." (PMID 31147529, 2019). "Although extensive research has been carried out on GDF10 being aberrantly methylated in various cancers, no single study reported this gene's specific methylation sites in much detail." (PMID 36262352, 2022). "Furthermore, we illustrated the expression of pyroptosis immune regulators across another∼10000 samples and revealed that CNST, GDF10, KCNC2, NAP1L2, NCOA7, and LINC00641 also revealed higher expression in cancer cells." (PMID 35620284, 2022). "Interestingly, GDF10 expression is mediated by SMAD2/3-dependent activating signals from the type III TGF-β receptor(TGFBR3), whose expression is also reduced in this type of cancer." (PMID 33173593, 2020).
GDF10 also shares sentences with these, for which no sentence is quoted: breast tumors (2 papers); hepatocellular carcinoma (2); non-small cell lung carcinoma (2); age (1); amyotrophic lateral sclerosis (1); brain injuries (1); cardiovascular disease (1); cerebral palsy (1); diabetes mellitus (1); diabetic foot ulcers (1); Hypercholesterolemia (1); Hypoxic-Ischemic Encephalopathy (1); ischemic stroke (1); left ventricular hypertrophy (1); lung fibrosis (1); myocardial infarction (1); myocardial ischemia (1); neurodegenerative disease (1); neurological disorders (1); Parkinson disease (1); sarcoidosis (1); squamous cell carcinoma (1); steatosis (1).